FHL1 (four and a half LIM domains 1)
Diseases named in the same sentence as FHL1 in open-access papers (continued):
Sharing a sentence is not in itself a finding about the gene and the disease.
Autoimmunity (1 paper, 2025). The occurrence of an immune reaction against the organism's own cells or tissues. "Some patients develop autoimmunity to FHL1 (granzyme B released by cytotoxic cells cleaves FHL1, and cleaved FHL1 fragments become neo-epitopes, likely initiating the development of autoantibodies), which later leads to muscle fiber damage." (PMID 40869293, 2025).
clubfoot (1 paper, 2013). The most common congenital deformation of the foot, occurring in 1 of 1,000 live births. "Our previous work showed that expression of FHL1 was downregulated in musculus flexor hallucis longus of congenital clubfoot, which demonstrated that downregulation in FHL1 expression is involved in the formation of skeletal muscle abnormalities in CCF." (PMID 24265776, 2013).
coronary atherosclerosis (1 paper, 2022). Atherosclerosis of the coronary vasculature. "In addition to MFGE8, we identified three additional previously unreported loci to be associated with coronary atherosclerosis, TMEM200A, PRG3 and FHL1 being the nearest genes of the lead variants." (PMID 35978133, 2022).
dermatomyositis (1 paper, 2022). Dermatomyositis (DM) is a type of idiopathic inflammatory myopathy characterized by evocative skin lesions and symmetrical proximal muscle weakness. "Of the five anti-HMGCR–positive patients with dermatomyositis, three were also positive for other MSAs (1 with anti-NXP2 and FHL1, 1 anti-Jo1, 1 anti–TIF1-γ autoantibodies)." (PMID 35603214, 2022).
desminopathies (1 paper, 2023). "Even cardiomyocytes can be affected, as in desminopathy, myotilinopathy and FHL1-related disorders." (PMID 37176163, 2023).
diabetes (1 paper, 2015). "This transcription factor leads to the inhibition of FHL1, IARS2, ARL6IP5, PSIP1 and PRPS1, some of which have been implicated in processes that are involved in the progression of different conditions leading to diabetes." (PMID 26302420, 2015).
endothelial dysfunction (1 paper, 2025). In vascular diseases, endothelial dysfunction is a systemic pathological state of the endothelium (the inner lining of blood vessels) and can be broadly defined as an imbalance between vasodilating and vasoconstricting substances produced by (or acting on) the endothelium. "A hallmark of LKP-induced endothelial dysfunction was the significant downregulation of mitochondrial genes (e.g., mt-Co1, mt-Atp6) and upregulation of stress-response genes (e.g., Gsn, Fhl1)." (PMID 41459160, 2025).
esophageal cancer (1 paper, 2020). A primary or metastatic malignant neoplasm involving the esophagus. "Results from this study support the utility of FHL1 expression as an independent prognostic factor for esophageal cancer." (PMID 32587768, 2020). "Importantly, FHL1 phosphorylation was elevated in tissues obtained from various human cancer types, including lung, liver, gastric, rectal, and esophageal cancers, although total FHL1 levels were decreased in these tumors." (PMID 32587768, 2020).
Fibroadenoma (1 paper, 2020). A benign tumor of the breast characterized by the presence of stromal and epithelial elements. "Furthermore, the expression of seven step-changing proteins (KRT10, KRT1, KRT6E, PLIN1, HBA2, FHL1, and ME2) were decreased in fibroadenoma tissues compared to fibroadenoma adjacent and normal tissues." (PMID 33194682, 2020).
Flavivirus Infections (1 paper, 2023). Infections with viruses of the genus FLAVIVIRUS, family FLAVIVIRIDAE. "Whether increased levels of FHL1 are a host-driven response to muscle damage, a response to soluble factor(s) from infiltrating leukocytes, or are directed by the virus, as seen in flavivirus infection to immunopathological effect, remains to be investigated." (PMID 37884534, 2023).
Hypocalcemia (1 paper, 2017). An abnormally decreased calcium concentration in the blood. "Nonetheless, due to the clinical assessment that the patient’s severe phenotype and early onset strongly suggest a genetic cause, we have decided to further pursue the connection between FHL1 and hypocalcemia." (PMID 28444561, 2017).
hypoparathyroidism (1 paper, 2017). Hypoparathyroidism is an endocrine disorder in which the parathyroid glands in the neck do not produce enough parathyroid hormone (PTH). "In summary, we have uncovered FHL1 as a novel potential regulator of calcium homeostasis in both fish and humans and have implicated it in isolated hypoparathyroidism." (PMID 28444561, 2017). "Indeed, when we over-expressed FHL1b in human cells, we observed strong and significant increase in activation of the human PTH gene, confirming that FHL1 loss of function in the patient might well be the etiologic factor leading to hypoparathyroidism." (PMID 28444561, 2017).
idiopathic pulmonary arterial hypertension (1 paper, 2022). A sporadic form of pulmonary arterial hypertension (PAH) characterized by elevated pulmonary arterial resistance leading to right heart failure. "Another study has also demonstrated that FHL1 is a prominently upregulated protein in lung tissues from patients with idiopathic pulmonary arterial hypertension and its overexpression enhances migration and proliferation of pulmonary artery SMCs." (PMID 36184652, 2022).
infertile (1 paper, 2022). "As shown by IHC, HOXA10 and FHL1 expression was significantly lower (p < 0.05) in the endometrial epithelial and stromal cells of infertile women with a GTD history than in those of the controls." (PMID 35120557, 2022).
leiomyoma (1 paper, 2016). A well-circumscribed benign smooth muscle neoplasm characterized by the presence of spindle cells with cigar-shaped nuclei, interlacing fascicles, and a whorled pattern. "In our study, we observed the upregulation of FHL1, a protein that mediates signaling, regulates the cytoskeleton-associated protein–protein interaction of transcription factors and has never previously been described as associated with leiomyomas." (PMID 27070597, 2016). "Among the proteins identified, four had never previously been associated with leiomyoma: isoform 2 of guanine nucleotide-binding protein G(I)/G(S)/G(T) subunit β-1, isoform 3 of polymerase I and transcript release factor, isoform 5 of prelamin-A/C and FHL1." (PMID 27070597, 2016).
lentivirus infection (1 paper, 2021). Virus diseases caused by the Lentivirus genus. "After lentivirus infection, the knockdown and overexpression efficiencies of FHL1 were confirmed by qRT-PCR and Western blot." (PMID 34335951, 2021).
liver cirrhosis (1 paper, 2002). "In an ELISA assay, employing the 196X mAb, the combined mean level of factor H and FHL-1 was higher in the cancer patient AF (758±312 μg ml−1, mean±s.d.; n=16) than in NHS (461±63 μg ml−1, n=8; Student's t-test, P<0.05) or in AF samples from liver cirrhosis patients (43±27 μg ml−1, n=6)." (PMID 12402151, 2002).
macular degeneration (1 paper, 2023). Loss of vision in the central portion of the retina (macula), secondary to retinal degeneration. "Previous studies have established a potential link between FHL-1 and early-onset macular drusen (EOMD), a form of macular degeneration with similar presentation to AMD but appearing at a younger age." (PMID 37471073, 2023).
major depression disorder (1 paper, 2020). "CFH/FHL-1 binding to MDA-modified bovine serum albumin (MDA-BSA) and CFH/FHL-1 concentrations were measured in plasma of 934 unrelated healthy individuals and of 896 unrelated patients with major depression disorder (MDD)." (PMID 32321835, 2020).
Obesity (1 paper, 2020). Accumulation of substantial excess body fat. "Overall, this study highlights the role of miR-96-5p in myogenesis via FHL1 suppression and suggests a novel regulatory mechanism for myogenesis mediated by miRNA in a background of obesity." (PMID 33322515, 2020). "Therefore, this study highlights the crucial role of miR-96-5p in myogenic differentiation through FHL1 suppression and suggests a novel miRNA-mediated myogenic regulatory mechanism in a background of obesity." (PMID 33322515, 2020).
osteoporosis (1 paper, 2019). A condition of reduced bone mass, with decreased cortical thickness and a decrease in the number and size of the trabeculae of cancellous bone (but normal chemical composition), resulting in increased fracture incidence. "Has-miR-133a-3p was involved in osteoclast formation, differentiation, apoptosis, and resorption, showing great promise as a potential therapeutic target for biomarkers and osteoporosis, and was found to regulate TGFBR2 and FHL1 expression in this study." (PMID 31737663, 2019).
retinoblastoma (1 paper, 2018). A malignant tumor that originates in the nuclear layer of the retina. "Moreover, the genetic variant rs1061170 (p.Y402H) in CFH which is a strong risk factor for AMD seems to influence the levels of ceramides in serum, and FHL-1 variants Y402 and H402 differentially regulate the expression of ceramide synthesis genes in retinoblastoma-derived cells." (PMID 30071029, 2018).
rheumatoid arthritis (1 paper, 2020). A chronic, systemic autoimmune disorder characterized by inflammation in the synovial membranes and articular surfaces. "To date, the synovial fluid expression levels of FH and FHL-1 in the settings of rheumatoid arthritis and the Bruch’s membrane have been determined." (PMID 33178228, 2020).
serous ovarian carcinoma (1 paper, 2002). "An analysis of a series of serous ovarian carcinoma samples (n=25) demonstrated that all tumours expressed factor H/FHL-1." (PMID 12402151, 2002).
squamous cell carcinoma (1 paper, 2014). A carcinoma arising from squamous epithelial cells. "In contrast, some reports show that FHL1 is expressed at a high level in a squamous cell carcinoma cell line." (PMID 24952875, 2014).
systemic sclerosis (1 paper, 2025). A chronic disorder, possibly autoimmune, marked by excessive production of collagen which results in hardening and thickening of body tissues. "In this study, we confirmed the presence of autoantibodies targeting the FHL1 protein in patients with IIM in 27% in the first available serum sample, but we also detected low levels of anti-FHL1 autoantibodies in patients with systemic sclerosis or SLE." (PMID 38833674, 2025).
thyroid tumor (1 paper, 2022). A benign or malignant neoplasm affecting the thyroid gland. "We also integrated differentially downregulated DEGs from the datasets and identified six downregulated DEGs, namely, MPPED2, TNFRSF11B, FHL1, CRABP1, MATN2, and TFF3, collectively known as thyroid tumor-downregulated genes (TTDGs)." (PMID 35990603, 2022).
upper respiratory tract infection (1 paper, 2024). "A λ light-chain dimer that targets SCR3 in the regulatory regions of Factor H and FHL1 and blocks Factor H and FHL1 regulation was identified in a 52-year-old female patient with an upper respiratory tract infection prior to clinic presentation." (PMID 39534179, 2024).
vasculitis (1 paper, 2025). "Some previously reported clinical associations with anti-FHL1 autoantibodies could not be replicated, such as dysphagia or vasculitis, which could have been overestimated in the original report on anti-FHL1 autoantibodies due to patient selection." (PMID 38833674, 2025).
tumor (51 papers, 2002 to 2025). "Among the genes of interest, FHL1 is a gene known to be associated with changes in cell proliferation, in particular in cancer progression, by suppressing tumor cell growth." (PMID 39519555, 2024). "A suppressive role of FHL1 in tumor cell growth associated with the cell cycle has also been documented." (PMID 32587768, 2020). "The results also showed that FHL1 expression were significantly associated with tumor grade (p = 0.025), p16 (p = 0.045), poorer OS (p = 0.004) and DFS (p = 0.005)." (PMID 26908444, 2016). "In the training cohort (n = 105), our results showed that low FHL1 mRNA levels were significantly associated with poorer tumor differentiation (p = 0.020) and worse OS (p = 0.018) or DFS (p = 0.038)." (PMID 26908444, 2016). "In addition, the results of PDAC tumor tissue IHC revealed that high expression of IMUP was associated with a low level of FHL1, while Pearson’s correlation analysis suggested that their IHC scores were negatively correlated." (PMID 35142956, 2023). "FHL1 is associated with multiple functions in both normal and tumor cells." (PMID 32587768, 2020). "A preliminary report from twelve years ago demonstrated Src tyrosine kinase-mediated suppression of FHL1 expression through phosphorylation of the focal adhesion adaptor protein, Crk-associated substrate (Cas), in v-Src-transformed cells that resulted in promotion of tumor cell growth." (PMID 32587768, 2020). "Another study reported that knockdown of FHL1 promoted tumor growth in nude mice, reinforcing its role as a tumor suppressor." (PMID 41439026, 2025). "In tumors, the expression of Fhl1 is upregulated or downregulated and plays a role in promoting or inhibiting tumor development." (PMID 41011134, 2025). "FHL1 has been confirmed as a tumor suppressor that inhibits cell growth, invasion, and cancer progression." (PMID 35142956, 2023). "We found that the gene expression of SOSTDC1, HMGA2, and FHL1 was significantly higher in tumor tissues than their paired adjacent normal tissues from 31 PRCC patients in TCGA database, especially that of HMGA2 (p < 0.001)." (PMID 37283291, 2023). "Results showed that FHL1-shRNA restored cell proliferation, colony formation, S phase arrest, and tumor xenograft growth in mice, which were inhibited by IMUP knockdown." (PMID 35142956, 2023). "Recently, FHL1 was found to be phosphorylated by the cytosolic tyrosine kinase Src, which switched FHL1 from a tumor suppressor to a cell growth accelerator." (PMID 36752296, 2023). "Most notably, Src inhibited expression of the Fhl1 tumor suppressor and induced expression the Pdpn tumor promoter, and this effect was reversed by contact normalization as previously reported." (PMID 35177067, 2022). "In order to validate our data indicating the low expression of FHL1 in CRC tumor tissue, we also checked the correlation between FHL1 expression and survival in TCGA database." (PMID 34335951, 2021). "On the other hand, FHL1 can function as an oncogenic protein that promotes tumor progression upon phosphorylation, reflecting complex roles in cancer." (PMID 32587768, 2020). "Previously, FHL1 has been reported to function as a tumor suppressor with inhibitory effects on cell growth, proliferation, and migration in various cancer cells." (PMID 33322515, 2020). "Through casein kinase 1 (CK1δ), FHL1 enhances phosphorylation of Smad proteins and promotes nuclear translocation of Smad4 to stimulate the tumor suppressor gene, p21, and suppresses the oncogene, c-myc." (PMID 32587768, 2020). "And, previous studies have shown the tumor-growth-inhibition effects of FHL1 and FHL2 was mediated by TGFβ/smad signaling." (PMID 31935687, 2020). "Under conditions of overexpression of Kindlin-2 in cells, both interactions between FHL1 and Src and FHL1 phosphorylation were suppressed and the tumor suppressor function of FHL1 was maintained." (PMID 32587768, 2020).
tumor (continued). "FHL1 is a well established tumor suppressor and several reports have confirmed its inhibitory effects on cell growth, migration, invasion, and metastasis." (PMID 32587768, 2020). "FHL1 is a tumor suppressor gene that acts downstream of the Src tyrosine kinase and the focal adhesion adaptor protein Crk-associated substrate (Cas) to specifically block anchorage-independent cell growth and migration." (PMID 30379883, 2018). "Summarily, in this study, we identified FHL1 as a novel epigenetic silencing target, discovered its function as a tumor suppressor and a novel therapeutic target in HNSCCs." (PMID 26908444, 2016). "Studies using clinical samples have shown that FHL1 expression is down-regulated in multiple human tumor types, including gastric cancer and hepatocarcinoma." (PMID 25272045, 2014). "Collectively, these data indicate that miR-410 introduction suppresses FHL1 expression and promotes tumor survival both in vitro and in vivo." (PMID 25272045, 2014). "FHL1 exerts tumor suppressor function via multiple mechanisms, including the activation of the TGF-β-like and Src-MAPK signaling pathways and protein interaction with ZO-1, HIF1α, and ERα." (PMID 25272045, 2014). "In this study, we accurately discriminated samples that had a high tumor content from normal breast tissue based on the previous demonstration that FHL1 and CLDN5 can serve as such predictors." (PMID 16091131, 2005). "All 27 tumor samples were correctly qualified as cancerous tissues using the two-gene signature (FHL1 and CLDN5)." (PMID 16091131, 2005). "Some tumour cells have also been found to secrete the soluble C regulators factor H (FH) and factor H-like protein 1 (FHL-1)." (PMID 15726105, 2005). "To analyse the production of factor H/FHL-1 by cultured tumour cells we first examined a panel of several cell lines." (PMID 12402151, 2002). "Furthermore, Dhx9, Dusp12, Fhl1, and Ifitm1 are each correlated with the invasion of tumor‐infiltrating immune cells into the microenvironment." (PMID 38193115, 2024). "However, although it contributes to the suppression of tumor growth and metastasis, recent studies have shown that FHL1 increases chemoradiotherapy resistance in some cancers." (PMID 35142956, 2023). "FHL1 has been reported as a tumor suppressor in many cancers." (PMID 35142956, 2023). "The human FHL1 gene, located on chromosome Xq26, has been reported as a tumor suppressor." (PMID 36752296, 2023). "For example, mCRPs along with factors H and FHL-1 could be present in soluble forms that might attach to tumor cells, leading to tumor resistance to complement activation." (PMID 35173724, 2022). "As a tumor suppressor gene, FHL1 is downregulated in a variety of tumors." (PMID 36212830, 2022). "In glioma, decreased FHL1 protein represses tumor growth via PI3K/AKT signaling transduction." (PMID 36017148, 2022). "Our data demonstrated that overexpression of FHL1 inhibited the proliferation, colony formation potential, and expression of CdK4 and Cyclin D1, whereas ablating FHL1 promoted proliferation and colony formation potential, suggesting that FHL1 acts as a tumor suppressor in CRC." (PMID 34335951, 2021). "Our data demonstrated that overexpression of FHL1 inhibited the proliferation, colony formation potential, and expression of CdK4 and Cyclin D1, whereas ablating FHL1 promoted their proliferation and colony formation potential, suggesting that FHL1 acts as a tumor suppressor in CRC." (PMID 34335951, 2021). "The results suggest that the role of FHL1 in tumor progression is dependent on the relative levels of Kindlin-2 and Src activity in cells, which determine whether FHL1 is anchored at focal adhesion sites and where it inhibits tumorigenesis." (PMID 32587768, 2020). "FHL1 appears to execute opposite functions in tumor and normal cells." (PMID 32587768, 2020). "Knockdown of BCLAF1 blocked phospho-FHL1-mediated tumor growth." (PMID 32587768, 2020).